ZNF575 (zinc finger protein 575)
Description:
May be involved in transcriptional regulation.
Synonyms: FLJ32567
Tractability: No criterion of Open Targets' tractability assessment is met for any kind of drug.
Gene: Protein-coding gene on chromosome 19 (43,525,497 to 43,536,498, forward strand). Ensembl gene ENSG00000176472.
Subcellular location: Nucleus
Subcellular location (Human Protein Atlas): Nucleoplasm; Cytosol; Nucleoli fibrillar center
Gene Ontology:
Molecular function: protein binding; DNA-binding transcription factor activity, RNA polymerase II-specific; RNA polymerase II cis-regulatory region sequence-specific DNA binding
Biological process: regulation of transcription by RNA polymerase II
Cellular component: nucleus
Genetic constraint (gnomAD): Loss-of-function variants: 17 observed, 15.66 expected, observed/expected ratio (o/e) 1.09, 90% interval 0.74 to 1.62. The upper end of that interval is the gene's LOEUF score, 1.62, which puts it in group 6 of 6, group 1 being the genes least tolerant of losing a copy. Missense variants: 351 observed, 328.51 expected, observed/expected ratio (o/e) 1.07, 90% interval 0.98 to 1.17. Synonymous variants: 145 observed, 138.52 expected, observed/expected ratio (o/e) 1.05, 90% interval 0.91 to 1.2.
Homologues: Orthologues: chimpanzee ZNF575 (99% identical), dog ZNF575 (91% identical), macaque ZNF575 (91% identical), pig ZNF575 (91% identical), guinea pig ZNF575 (86% identical), mouse Zfp575 (82% identical), rat Zfp575 (80% identical), rabbit ZNF575 (74% identical). Paralogues in human: ZNF362 (30% identical), PRDM1 (29% identical), ZNF384 (28% identical), HIC1 (27% identical), ZNF76 (27% identical), PRDM14 (27% identical), ZNF143 (27% identical), MTF1 (25% identical), PRDM10 (25% identical), PATZ1 (24% identical), HIC2 (24% identical), MAZ (24% identical), and 24 more.
Diseases named in the same sentence as ZNF575 in open-access papers:
ZNF575 is named in the same sentence as 4 diseases in open-access papers, as found by Europe PMC text mining. Sharing a sentence is not in itself a finding about the gene and the disease. The quoted sentences say what the papers report.
colorectal cancer (2 papers, 2023 to 2024). A primary or metastatic malignant neoplasm that affects the colon or rectum. "In the present study, we aimed to determine the function and expression of ZNF575 in colorectal cancer." (PMID 37305392, 2023). "Proliferation assay, colony formation assay, and tumor model in mice were used to investigate the function of ZNF575 after ectopic expression of ZNF575 in colorectal cancer (CRC) cells." (PMID 37305392, 2023).
cancer (1 paper, 2023). A tumor composed of atypical neoplastic, often pleomorphic cells that invade other tissues. "Bu further experiments are needed to investigate the role and related molecular mechanism of ZNF575 in regulating other characteristics of cancer, such as metastasis, therapeutic responses, and immune environment." (PMID 37305392, 2023). "But further experiments are needed to investigate the role of ZNF575 in regulating cancer cell metastasis, therapeutic responses, and the immune environment." (PMID 37305392, 2023). "Zinc-finger proteins play different roles in cancer; however, the function of zinc-finger protein ZNF575 in cancer remains unclear." (PMID 37305392, 2023). "The findings of our study would present evidence to clarify the role of ZNF575 in cancer." (PMID 37305392, 2023). "The present study demonstrated the function, underlying mechanism, expression, and the prognosis-predicting role of ZNF575 in CRC, which indicated that ZNF575 would be a potential prognostic predictor and therapeutic target for CRC and other cancers." (PMID 37305392, 2023).
tumor (1 paper, 2023). "Collectively, ZNF575 dramatically inhibited CRC tumor growth in vivo." (PMID 37305392, 2023). "We demonstrated that the ZNF575 dramatically impaired CRC cell proliferation in vitro, accompanied by tumor growth inhibition in mice." (PMID 37305392, 2023). "The novel findings in our study demonstrate the anti-tumor effect of ZNF575 in CRC, as evidenced by the inhibitory role of ZNF575 in CRC cell proliferation and tumor growth." (PMID 37305392, 2023).
ZNF575 also shares sentences with these, for which no sentence is quoted: endometrial carcinoma (1 paper).